NCAPH (non-SMC condensin I complex subunit H)
Diseases named in the same sentence as NCAPH in open-access papers (continued):
Sharing a sentence is not in itself a finding about the gene and the disease.
cancer (31 papers, 2015 to 2025). A tumor composed of atypical neoplastic, often pleomorphic cells that invade other tissues. "Research indicates that NCAPH is implicated in the pathogenesis of various malignant tumors, impacting patient survival and prognosis." (PMID 41210692, 2025). "We found that these drugs can easily bind to these targets and have a relatively stable conformation, and the core target is closely related to tumor development and may be closely associated with the cancer-promoting effect of high expression of NCAPH." (PMID 41210692, 2025). "Therefore, overexpression of NCAPH has been linked to increased tumor growth, invasion, and metastasis, while its downregulation can impair cell proliferation and induce apoptosis in cancer cells." (PMID 39136001, 2024). "Based on our findings, we hypothesize that NCAPH may be associated with human carcinogenesis and could be a potential therapeutic target for human cancer." (PMID 31784646, 2019). "However, up to now, the function of NCAPH in human cancers is largely unknown, and the underlying molecular mechanism has not been reported." (PMID 33311486, 2020). "Non-SMC (Structural Maintenance of Chromosomes) condensin I complex subunit H (NCAPH) has been shown to facilitate progression and predict adverse prognostic outcome in many cancer types." (PMID 38587786, 2025). "This study used gene expression profile data to reveal that NCAPH is overexpressed in almost all cancers, including LGG, which is consistent with the conclusions of previous investigators." (PMID 41210692, 2025). "In pan-cancer analysis, NCAPH mRNA expression levels were found to be elevated across a range of tumor types, including LGG." (PMID 41210692, 2025). "NCAPH plays a critical role in tumorigenesis and progression across multiple cancer types; however, its specific role in PCa has yet to be fully understood." (PMID 39991770, 2025). "NCAPH can promote the proliferation and mobility of various cancer cells through PI3K/AKT and MEK/ERK signaling pathways." (PMID 38587786, 2025). "In order to examine the variance in NCAPH expression across human normal tissues, cancer tissues, and cells, we conducted an analysis utilizing the TCGA, GTEx, and HPA databases to assess RNA sequencing data from a range of tissues and diseases." (PMID 41210692, 2025). "For further understand the prognostic value of NCAPH in different cancer types, we combined TCGA clinical data and RNA-seq data of above 19 cancers to plot Kaplan–Meier (K–M) survival curve." (PMID 38587786, 2025). "The investigation in our study focused on the expression of NCAPH across a range of human tissues, encompassing brain tissues, brain cells, and pan-cancer samples." (PMID 41210692, 2025). "Studies have found that NCAPH, as an oncogene, plays important roles in the occurrence and development of several cancers, significantly affecting the survival and prognosis of patients." (PMID 41210692, 2025). "Aberrant expression of the NCAPH gene has been found in multiple cancer types, including breast 8, lung 9, and bladder cancer." (PMID 39991770, 2025). "The most frequent genes were CKAP2L (Cytoskeleton Associated Protein 2 Like), NCAPH (Non-SMC Condensin I Complex Subunit H), and SGO2 (Shugoshin 2), which were the top differential genes in more than 50% of cancers." (PMID 38396175, 2024). "In NSCLC, miR-133b targeting NCAPH boosted β-catenin degradation while decreasing cancer stem cell maintenance." (PMID 38755247, 2024). "And some microRNAs also target NCAPH to promote the degradation of β-catenin to reduce cancer stem cell maintenance." (PMID 36741311, 2023). "Non‐SMC condensin I complex subunit H (NCAPH) is reported to play an important role and be a poor prognostic factor in various cancers." (PMID 36642844, 2023). "NCAPH was found to be overexpressed in different cancer types promoting tumorigenesis and possibly metastasis." (PMID 36900109, 2023).
cancer (continued). "It was confirmed that hsa-miR-133b targeted NCAPH to promote β-catenin degradation and reduced cancer stem cell maintenance in NSCLC." (PMID 38180107, 2023). "The highly expressed NCAPH can promote the glycolysis of cancer cells, increase the expression of PD-L1 and induce resistance to anti-PD-1 therapy by stabilizing the β-catenin protein." (PMID 37582735, 2023). "To further confirm the important role of NCAPH in cancer, we analyzed the expression of NCAPH in various cancers." (PMID 33311486, 2020). "Downregulation of NCAPH inhibited the proliferation, migration, and invasion of several cancer cells significantly." (PMID 33311486, 2020). "Firstly, we explored the expression of NCAPH in different cancer types." (PMID 38587786, 2025). "Moreover, down-regulation of NCAPH has been reported to significantly inhibit the progression of several cancer cell lines." (PMID 38587786, 2025). "Additionally, a comprehensive analysis of 32 cancers and their corresponding adjacent tissues demonstrated that NCAPH exhibited high expression levels in the majority of cancers, notably in LGG." (PMID 41210692, 2025). "NCAPH) plays a crucial role in cancer development and progression." (PMID 39136001, 2024). "However, the potential role of NCAPH in the etiology of many cancers, particularly LUAD, remains debatable." (PMID 38755247, 2024). "Integrated analysis of TCGA showed that NCAPH was overexpressed across cancers, including LUAD." (PMID 35688915, 2022). "The growth promoting effect of NCAPH was also reported in several other cancer cells." (PMID 34768935, 2021). "NCAPH has been demonstrated to be elevated in a large amount of human cancers." (PMID 34399777, 2021). "High NCAPH expression also suggests a poor prognosis in prostate and rectal cancer patients." (PMID 32528520, 2020). "Patients with high NCAPH expression had a significantly better survival outcomes than those with low-expression, suggesting that NCAPH-induced cell proliferation might sensitize cancer cells to adjuvant therapy." (PMID 33311486, 2020). "To elucidate whether NCAPH influences the migration and invasion of cancer cells via the regulation of the EMT process, we tested the effects of NCAPH on the expression levels of EMT related proteins in HeLa and SiHa cells by Western Blot analysis and immunofluorescent staining." (PMID 33311486, 2020). "In the case of new potential markers, the ZWINT and CONDENSIN I subunits NCAPH, SMC2, and SMC4 all showed similar expression levels displayed by markers in the first circuit, even sharing the same clustering of cancer types." (PMID 40430225, 2025). "NCAPG, NCAPH and ASPM have strong positive correlations with NCAPD2 expression in different cancers, especially in THYM." (PMID 38172945, 2024). "Co-expression network analysis showed that CDCA3, GSG2, KIF2C, NCAPH and PLK1 were positively correlated with ORC1 in cancer, and the functional enrichment mainly included cytosol, ATP binding and cell division." (PMID 37833711, 2023). "Co-expression network analysis showed that CDCA3, GSG2, KIF2C, NCAPH and PLK1 were positively correlated with ORC1 in cancer, and enrichment analysis showed a correlation with cytosol, ATP binding and cell division." (PMID 37833711, 2023). "Among the cancer driver genes that experienced epigenetic changes in at least five cancer types, we identified eight genes: CEP55, PIF1, RRM2, NCAPH, ZEB2, CIT, FLI1, and PCDH17." (PMID 31900418, 2020). "Using publicly available patient derived datasets obtained from TCGA, we determined that all eight condensin genes (SMC2, SMC4, NCAPD2, NCAPD3, NCAPG, NCAPG2, NCAPH, and NCAPH2) are frequently altered in at least 12 common cancer types." (PMID 31357676, 2019). "Moreover, based on the blue module genes screened by WGCNA and existing researches, AURKA, TPX2, CHEK1, and PLK1 were found to be highly related to NCAPH and were involved in the regulation of PI3K/AKT pathway in cancer." (PMID 38587786, 2025).
cancer (continued). "As for the comparison between 33 different cancer types and their normal counterparts, the expression of NCAPH was not uniformly upregulated in all 33 cancers." (PMID 38587786, 2025). "Similarly, the non-structural maintenance of chromosomes condensing I complex subunit H (NCAPH) also facilitated cell proliferation, migration, invasion, and epithelial-to-mesenchymal transition (EMT) of cancer." (PMID 36741311, 2023). "Although NCAPH plays a central role in mitotic chromosome assembly and segregation in humans, there is not much data on the relationship between NCAPH and cancer in the literature." (PMID 35327439, 2022). "In the ERBB2 network, we also found a subnetwork of direct protein–protein interactions formed by the non-SMC condensin I complexes (NCAPD2, NCAPG, NCAPH), a vital complex associated with the ERBB2 signaling pathway and cancer development." (PMID 33424936, 2020). "Non-SMC condensin I complex subunit H (NCAPH) plays a regulatory role in various cancers." (PMID 35688915, 2022).
tumor (26 papers, 2012 to 2025). "Given our findings that elevated NCAPH levels correlate with poorer outcomes in luminal ERBB2 tumours in transgenic mice, we identified a gene signature associated with high NCAPH levels." (PMID 38344872, 2024). "Previously, we found that the ectopic expression of NCAPH, a regulatory subunit of condensed protein complexes, significantly enhanced the proliferation of tumor cells; however, the underlying mechanisms were unclear." (PMID 39103348, 2024). "We found that the overexpression of NCAPH is associated with poor prognosis, specifically in luminal A tumours and HER2+ luminal tumours." (PMID 38344872, 2024). "Significantly, high levels of NCAPH in luminal A tumours were associated with poor response to endocrine therapy and chemotherapy in the long‐term follow‐up." (PMID 38344872, 2024). "This study examined the expression of NCAPH in tumor tissues and its association with immune infiltrates and prognostic roles in LUAD patients." (PMID 35688915, 2022). "However, elevated NCAPH levels in patients with tumours have been associated with a better prognosis and survival rate than in patients with low levels of NCAPH." (PMID 38344872, 2024). "NCAPH was linked to oncogenesis and tumor growth in several studies." (PMID 38755247, 2024). "Paradoxically, elevated NCAPH levels were associated with good evolution of basal tumours." (PMID 38344872, 2024). "High levels of NCAPH were associated with poor outcome, especially in luminal A tumours." (PMID 38344872, 2024). "It is plausible that patients with luminal A tumours, exhibiting high levels of NCAPH and displaying the associated signature could represent a distinct subgroup of tumours." (PMID 38344872, 2024). "The specific association between high NCAPH levels and poor prognosis in luminal tumours may be related to the ability of condensin I complex to bind to ER enhancers." (PMID 38344872, 2024). "This study highlights the significant pro-tumor role of NCAPH in PCa and suggests its potential as a therapeutic target." (PMID 39991770, 2025). "We also observed a substantial decrease in NCAPH and Ki67 expression in NCAPH-KD xenograft tumor tissues." (PMID 39991770, 2025). "NCAPH's involvement in coordinating immune cell infiltration into the tumor microenvironment suggests a role in promoting immune tolerance in LGG, making it a potential target for immunotherapy." (PMID 41210692, 2025). "The identification of NCAPH as a novel tumor promoter represents a promising new therapeutic target." (PMID 39991770, 2025). "Combining NCAPH-KD with an mTOR inhibitor (Everolimus, Eve) or a cyclin-dependent kinase inhibitor (Flavopiridol, Flav) shows a promising anti-tumor effect in PCa cells both in vitro and in vivo." (PMID 39991770, 2025). "Specifically, we observed a marginally reduced tumour incidence in instances where NCAPH is induced as a primary oncogenic event in normal breast tissue, as compared to non‐induced cases." (PMID 38344872, 2024). "In recent studies, oncogenes such as NCAPH can be targeted by some microRNAs to participate in tumor occurrence." (PMID 38755247, 2024). "In human tumours, a robust positive correlation was discerned between NCAPH expression and proliferation markers (Ki67) or genomic instability markers (H2AX and CHEK1)." (PMID 38344872, 2024). "According to recent investigations, NCAPH appears to be involved in various tumor cell biological activities." (PMID 38755247, 2024). "The effect of the mir-1976-induced decrease in the number of tumor nodules was considerably reversed by the overexpression of NCAPH (P < 0.001)." (PMID 38755247, 2024).
tumor (continued). "Together, these findings propose that NCAPH overexpression in ERBB2 tumours engenders more aggressive histopathology, solid tumours with high mitotic indices, and enhanced vascularisation and cell proliferation." (PMID 38344872, 2024). "Following that, we discovered that the mir-1976/NCAPH axis plays a critical role in tumor growth and metastasis in mouse models." (PMID 38755247, 2024). "We evaluated NCAPH levels by IHC in a cohort of patients with luminal A tumours, and again, we confirmed the higher NCAPH protein levels in patients with a poor outcome (presence of liver metastases) than in those who evolved well in the 10‐year follow‐up." (PMID 38344872, 2024). "The role of NCAPH in immunoregulation also was explored by flow cytometry, T cell‐mediated tumour cell killing assay and immune‐competent mouse model." (PMID 36642844, 2023). "By using TISIDB, we found that NCAPH expression was significantly correlated to multiple TILs (tumour‐infiltrating lymphocytes), immunoinhibitors, immunostimulators, MHCs, chemokines and receptors, indicating the potential immune regulatory function of NCAPH." (PMID 36642844, 2023). "Increased NCAPH expression was closely related to large tumour size, higher histologic grades and advanced TNM stages and poor prognosis in ccRCC patients." (PMID 36642844, 2023). "Of note, contrast to SMC4, the patients with NCAPH overexpression in colon cancerous tissues had a significantly better prognosis and survival rate than those with low-expression of NCAPH in tumor tissues." (PMID 34557090, 2021). "Future personalized therapies targeting NCAPH is expected to induce robust antitumor responses not only reducing tumor growth ability, but also decreasing the expression of E7." (PMID 33311486, 2020). "Strikingly, NCAPH, another subunit of condensin 1, which has also been shown to be a tumor-promoting factor, is expressed in hormone-sensitive prostate cancer and involved in resistance to castration." (PMID 32683421, 2020). "Our results showed that NCAPH promoted tumor proliferation, migration, and invasion in vitro and in vivo." (PMID 31523845, 2019). "To further validate the tumor‐promoting function of NCAPH, we performed an in vivo xenograft assay using nude mice." (PMID 31523845, 2019). "In particular, the depletion of NCAPH inhibits the proliferation and migration of colon cancer (CC) cells in vitro and blocks CC xenograft tumor formation." (PMID 31784646, 2019). "More importantly, we found that knockdown of NCAPH decreased the xenograft tumor formation of HCT116 in vivo." (PMID 28300828, 2017). "We found that depletion of NCAPH inhibits CC cell proliferation, migration in vitro and xenograft tumor formation in vivo." (PMID 28300828, 2017). "And, we also found that the NCAPH high expression in tumor tissues of colon patients had a significantly better prognosis and survival rate than low-expression patients." (PMID 28300828, 2017). "We also found that knockdown of NCAPH inhibits CC cells proliferation, migration in vitro and xenograft tumor formation in vivo, possibly through inhibiting cell cycle transition and inducing cellular apoptosis." (PMID 28300828, 2017). "Here, we conduct a comprehensive analysis of NCAPH expression, abundance of cell subsets in single-cell cohorts, prognosis, co-localization, epigenetic alterations, functional enrichment, tumor immune-related features, immunotherapy response, drug sensitivity, and molecular docking in LGG." (PMID 41210692, 2025). "Furthermore, NCAPH gene silencing (NCAPH-KD) significantly inhibits tumor growth in a xenograft nude mouse model of PCa in vivo." (PMID 39991770, 2025). "Notably, combining NCAPH knockdown with an mTOR inhibitor (Everolimus) or a cyclin-dependent kinase inhibitor (Flavopiridol) demonstrated promising anti-tumor effects both in vitro and in vivo." (PMID 39991770, 2025). "Remarkably, tumours induced by NCAPH overexpression demonstrated a higher mitotic index." (PMID 38344872, 2024).